LMOD1 (leiomodin 1)
Diseases named in the same sentence as LMOD1 in open-access papers (continued):
Sharing a sentence is not in itself a finding about the gene and the disease.
unstable angina (1 paper, 2022). "In contrast, we found a statistically significant higher prevalence of the PHACTR1 rs9349379 G allele and the LMOD1 rs2820315 T allele in the group of patients with unstable angina." (PMID 35054067, 2022). "The association between these alleles and unstable angina was confirmed by multivariate logistic regression analysis, in which the number of G (PHACTR1 rs9349379) and T (LMOD1 rs2820315) alleles was an independent risk factor for unstable angina." (PMID 35054067, 2022). "The results of our study suggest an association between PHACTR1 rs9349379 and LMOD1 rs2820315 polymorphisms and unstable angina." (PMID 35054067, 2022). "The aim of this study was to evaluate the association between the PECAM1 (rs1867624), COL4A2 (rs4773144), PHACTR1 (rs9349379) and LMOD1 (rs2820315) gene polymorphisms and the risk of unstable angina." (PMID 35054067, 2022). "The presence of PHACTR1 rs9349379 G and LMOD1 rs2820315 T alleles is a risk factor for unstable angina." (PMID 35054067, 2022). "The current study found a significant increase in the risk of unstable angina in carriers of the LMOD1 rs2820315 T allele." (PMID 35054067, 2022). "The association between these alleles and unstable angina was confirmed by multivariate logistic regression analysis, in which the number of the G (PHACTR1 rs9349379) and T (LMOD1 rs2820315) alleles was an independent risk factor for unstable angina." (PMID 35054067, 2022). "The results of this study suggest that PHACTR1 rs9349379 and LMOD1 rs2820315 gene polymorphisms are associated with an increased risk of unstable angina." (PMID 35054067, 2022). "The results suggest an association between PHACTR1 rs9349379 and LMOD1 rs2820315 polymorphisms and the risk of unstable angina." (PMID 35054067, 2022).
visceral myopathy (1 paper, 2018). "More recently, a homozygous nonsense mutation in LMOD1 has been linked to a rare congenital visceral myopathy called megacystis microcolon intestinal hypoperistalsis syndrome (MMIHS)." (PMID 30444878, 2018). "This is supported by the recent identification of a recessive mutation in a premature stop codon of LMOD1 as a cause of a rare congenital visceral myopathy, MMIHS, which usually arises due to autosomal dominant mutations in the smooth muscle enriched actin gamma 2 (ACTG2) gene." (PMID 30444878, 2018).
cancer (7 papers, 2020 to 2025). A tumor composed of atypical neoplastic, often pleomorphic cells that invade other tissues. "LMOD1 not only promotes the activation of cancer-associated fibroblasts (CAFs) but also inhibits the Epithelial-mesenchymal transition (EMT) program in cancer cells." (PMID 38849852, 2024). "Our findings highlight several known joint susceptibility loci for CAD and cancer, including FKBP5, CUX2, and LMOD1, validating the pleiotropy analysis approach employed by PLACO." (PMID 40874306, 2025). "The expression of LMOD1 in cancer tissues was significantly higher than that in adjacent tissues, and the difference was statistically significant (P = 0.014)." (PMID 35488236, 2022). "Immunohistochemistry showed that LMOD1 was highly expressed in cancer tissues, and the prognosis of patients with high LMOD1 expression was poor." (PMID 35488236, 2022). "As expected, most up-regulated proteins are related to cancer genes, with seven of them known to be enhanced in PCa (SYNM, DES, MYH11, TAGLN, CNN1, LMOD1, and PGM5)." (PMID 38052461, 2024).
tumor (4 papers, 2015 to 2023). "Meanwhile expression of gene DPT, SMOC2, GLP2R, FBLN5 and LMOD1 were down-regulated in tumor tissues." (PMID 25970782, 2015).
myopathies (2 papers, 2020 to 2024). "The leiomodin (Lmod) family of actin-binding proteins play a critical role in muscle function, highlighted by the fact that mutations in all three family members (LMOD1-3) result in human myopathies." (PMID 38748723, 2024).
neurologic disease (1 paper, 2020). "This would explain why adults from O. volvulus endemic regions may have leiomodin-1 autoantibodies without any neurologic disease." (PMID 33321732, 2020).
LMOD1 also shares sentences with these, for which no sentence is quoted: colorectal cancer (2 papers); prostate carcinoma (2); schizophrenia (2); Brain atrophy (1); breast tumors (1); cholelithiasis (1); co-infection (1); diabetes (1); dilated cardiomyopathy (1); dissection (1); Duodenal stenosis (1); endometrial cancer (1); glioma (1); hemorrhage (1); hydronephrosis (1); infection (1); inflammation (1); insomnia (1); liver cancer (1); mitochondrial disease (1); myopia (1); neuropathy (1); Obesity (1); onchocerciasis (1); parasitic infection (1); thoracic aortic aneurysm (1); vasculitis (1).